CCL2 (C-C motif chemokine ligand 2)
Diseases named in the same sentence as CCL2 in open-access papers (continued):
Sharing a sentence is not in itself a finding about the gene and the disease.
oral cancer (16 papers, 2015 to 2026). "Mechanistically, uptake of EVs derived from oral cancer cells by monocytes caused activation of the inflammatory pathway, NF-κB activation, and establishment of a pro-inflammatory and pro-tumorigenic milieu marked by increased levels of IL-6, CCL2, PEG2 and MMP9 levels." (PMID 30410681, 2018). "N4BP1 is an endoribonuclease that specifically regulates a subset of mRNA targets (including CCL2 and GM-CSF) and plays an essential role in oral cancer." (PMID 41513619, 2026). "In our study, the observed association (OR = 0.78, 95% CI 0.32–0.99, P = .046) between CCL2 levels and oral cancer suggests a nuanced, protective role of CCL2 against oral cancer, highlighting the complex interplay of cytokines in cancer progression." (PMID 40489865, 2025). "In this study, we confirmed that fasting-mimicking diets not only directly enhances the sensitivity of oral cancer cells to gefitinib but also indirectly improves efficacy by attenuating CCL2-mediated TAMs recruitment under the gefitinib treatment environment." (PMID 40808689, 2025). "Our study goes beyond identifying correlations by demonstrating that specific cytokines, such as CCL2 and CCL8, have a causal role in oral cancer risk, revealing mechanisms behind cancer development." (PMID 40489865, 2025). "In oral cancer, stroma-derived CCL2 is a key player in recruiting myeloid-derived stem cells that express a receptor of CCL2, CCR2, from the bone marrow to the tumor microenvironment." (PMID 39201718, 2024). "In conclusion, oral cancer stroma–secreted CCL2 is a key signal for recruiting CCR2+ MDSCs from BM to the TME." (PMID 34874922, 2022). "In another study, the critical role of miR-124 in oral carcinoma development has been investigated as it targets Chemokine (C-C motif) Ligand 2 (CCL2) and Interleukin 8 (IL8) in both CAFs and oral cancer cells." (PMID 34946938, 2021). "Monocyte chemoattractant protein-1 (MCP-1, CCL2) is implicated in various inflammatory conditions and pathological processes, including oral cancer." (PMID 33330077, 2020). "Similarly, a CCL7 neutralizing antibody has been shown to inhibit CCL7-induced invasion and migration of oral carcinoma cells, and anti-CCL2 and-CCR3 antibodies are also being evaluated." (PMID 26046767, 2015). "Therapeutic Targets: Our identification of cytokines such as CCL2 and CCL8 as key drivers of oral cancer progression presents opportunities for therapeutic targeting." (PMID 40489865, 2025). "CCL2/CCR2 and intercellular adhesion molecule-1 (ICAM-1) are other important pathways that stimulate the recruitment of TAMs into oral cancers." (PMID 37221555, 2023). "In oral cancer cells and monocytes, the expression of TNF-α and CCL2 was increased after HAR1A knockdown and decreased after ALPK1 knockdown." (PMID 36139553, 2022). "Transcriptome profiling identified CCL2 and GM-CSF as downstream targets of N4BP1 in oral cancer." (PMID 41513619, 2026). "CAFs can also release CCL2, leading to the recruitment of CCR2 + MDSCs into oral cancer." (PMID 37221555, 2023). "Of note, MCP-1 (also known as CCL2) has been reported to be secreted by CAF at elevated levels, promoting cancer progression and migration in HCC as well as in oral cancer." (PMID 35628911, 2022). "Together, these data indicate that BM cells are recruited into the oral cancer TME through the action of the stroma factor CCL2 and not by SDF-1 and HGF." (PMID 34874922, 2022). "Suppression of chemoattracts such as CCL2/CCR2 and EGFR may be intriguing for oral cancer therapy." (PMID 37221555, 2023).
synovitis (16 papers, 2014 to 2025). Inflammation of a synovial membrane. "An increase in CCL2 concentration was seen at 6, 12, and 24 h post-induction of synovitis with differences from the contralateral limb at 6 and 24 h." (PMID 33980227, 2021). "Interestingly, at follow-up synovitis increased again evidenced at the macroscopic and microscopic level and the increased SF IL-8 and CCL2 levels." (PMID 36313973, 2023). "Interestingly, HtrA2 levels in the SF of RA patients were elevated in proportion to synovitis severity and correlated with the expression of proinflammation cytokines and chemokines, such as IL-6, IL-8, and CCL2." (PMID 37287073, 2023). "Whereas CCL2 and CCL3 returned to baseline levels within 24 h, CCL5 and CCL11 remained elevated from baseline for 72 h in the synovitis model." (PMID 33980227, 2021).
thrombosis (16 papers, 2011 to 2025). "In the time course of venous thrombosis simulated in a mouse model, CCL2 levels increase in the vein wall and, to a lesser extent, in the thrombus itself by day seven." (PMID 37954596, 2023). "Gas6 can amplify endothelial cell activation through TF expression, collect platelets and leukocytes to the endothelial cell membrane, and promote the recruitment of monocytes through a CCR2/CCL2-dependent mechanism during venous thrombosis." (PMID 35444662, 2022). "Co-culture of APS monocytes with LPS increased the expression of IL-1β, IL-6, IL-23, TLR2, CCL2, and CXCL10 genes to improve the sensitivity to LPS and contribute to the formation of thrombosis, but the response was weak in healthy donor cells." (PMID 37332592, 2023).
vasculitis (16 papers, 2009 to 2025). "Both genetic deficiency of the MCP-1 receptor (CCR2) or MCP-1/CCL2 antagonism improved LN and vasculitis in MRL/lpr mice." (PMID 34307414, 2021). "As vasculitis and elevated monocyte numbers are typical findings of SINS, CCL2 arises as a strong candidate gene in SINS pathogenesis." (PMID 39825377, 2025). "This study revealed the effects of LA on endothelial cell activation, NLRP3, IL-1β, TNF-α, IL-32, and CCL-2, VCAM-1, MCP-1, and the spleen tyrosine kinase (Syk)--p38/JNK signaling axis and its effect on vasculitis in rats." (PMID 30158835, 2018). "The elevations of CCL2, CXCL10, and GM-CSF in severe disease reported here could contribute to monocyte recruitment and activation leading to this vasculitis, alongside the role of GM-CSF in the recruitment of neutrophils to the pulmonary vasculature." (PMID 33692097, 2021). "Elevated MCP-1/CCL2 and IP-10/CXCL10 likely explained the accumulation of inflammatory cells in the lung including the observed neutrophils and monocytes, and development of vasculitis that likely contributed to morbidity and mortality." (PMID 33257679, 2020). "More recently, we have demonstrated that Dectin-2-mediated CCL2 produced by tissue-resident macrophages in the aortic root and coronary arteries may be the key initiator of vascular inflammation in the CAWS-induced vasculitis." (PMID 33150252, 2020). "For comparison the prototype Th2 chemokine (C-C motif) ligand 2 (CCL2) was not significantly different in patients with MC+HCV and active vasculitis than in MC patients, and it suggests that the Th1 CXCL10 chemokine is specifically involved in the appearance of vasculitis in these patients." (PMID 22611419, 2012).
amyotrophic lateral sclerosis (15 papers, 2011 to 2023). Amyotrophic lateral sclerosis (ALS) is a neurodegenerative disease characterized by progressive muscular paralysis reflecting degeneration of motor neurons in the primary motor cortex, corticospinal tracts, brainstem and spinal cord. "Baricitinib is being currently evaluated in a phase I/II basket trial in 20 patients with MCI, mild AD or Amyotrophic Lateral Sclerosis who must have elevated levels of the inflammatory cytokine CCL2 in CSF (NCT05189106)." (PMID 37332353, 2023). "An induction of neuronal CCL2 expression was described in response to various types of injury and degeneration such as ischemia, Alzheimer’s disease, MS, axonal injury, amyotrophic lateral sclerosis (ALS) or peripheral nerve injury." (PMID 30319362, 2018). "We have earlier shown that protein levels of vascular endothelial growth factor-A (VEGF-A) and chemokine ligand-2 (CCL2) were elevated in Indian amyotrophic lateral sclerosis (ALS) patients." (PMID 21906274, 2011). "Vascular endothelial growth factor-A (VEGF-A) and chemokne ligand-2 (CCL2) levels have been examined in Amyotrophic Lateral Sclerosis (ALS) patients in Western countries." (PMID 21569455, 2011). "We earlier reported elevated chemokine ligand-2 (CCL2) in Indian amyotrophic lateral sclerosis (ALS) patients." (PMID 22685564, 2012).
interstitial lung disease (15 papers, 2005 to 2025). A diverse group of lung diseases that affect the lung parenchyma. "Levels of circulating CCL2 were elevated in SSc patients, especially in those with early dcSSc or interstitial lung disease." (PMID 23845159, 2013). "High IL-7 levels were characteristic of SSc-associated interstitial lung disease (ILD) and, in addition, when compared with ILD-negative SSc patients, ILD-positive SSc patients revealed higher IL-4, IL-6, IL-8, and CCL2 (MCP-1) BALF levels." (PMID 19615053, 2009). "In addition, CCL2 levels in BALF in IPF are significantly higher than those in other types of interstitial lung disease (ILD), including interstitial pneumonia collagen vascular disease (IP-CVD) and chronic interstitial pneumonia (CIP)." (PMID 36830702, 2023).
kidney stones (15 papers, 2015 to 2025). "In this study, we have shown that an epistatic interaction between the CASR rs7652589 SNP (risk allele A) and CCL2 rs1024611 (risk allele G) is associated with nephrolithiasis-related ESRD requiring regular dialysis treatment." (PMID 27739473, 2016). "The A allele of CASR rs7652589 was also a significant determinant of nephrolithiasis-related ESRD among other possible determinants such as gender, age, serum concentrations of Ca and PTH, and the G allele of CCL2 rs1024611." (PMID 27739473, 2016). "In our recent study, there was an epistatic interaction between CASR rs7652589 and rs1024611 in the chemokine (C-C motif) ligand 2 gene (CCL2) in nephrolithiasis-related ESRD." (PMID 27642296, 2016). "It should be noted that CCL2 rs1024611 and IL18 rs360719 yielded borderline associations with nephrolithiasis-related ESRD simultaneously with a significant association with the CASR rs7652589 SNP." (PMID 27739473, 2016). "The A allele of CASR rs7652589 was recognized in our study as a risk allele for severe nephrolithiasis, among other possible factors, such as gender, age, serum concentrations of Ca and PTH, and the G allele of CCL2 rs1024611." (PMID 27739473, 2016). "Gender, age, serum concentrations of Ca and PTH, the G allele of CCL2 -2518 A > G (rs1024611), and the A allele of CASR rs7652589 were entered into the multivariate stepwise linear regression model as possible determinants of nephrolithiasis-related ESRD." (PMID 27739473, 2016). "In glyoxylic acid-induced nephrolithiasis murine models, CCR2 inhibitors significantly reduce tubular epithelial injury and crystal deposition, likely through disrupting the CCL2/CCR2-axis-mediated cross-talk between crystal-laden tubular cells and pro-inflammatory macrophages." (PMID 40867535, 2025).
liver cirrhosis (15 papers, 2009 to 2024). "In a zebrafish model with FOCAD deficiency, liver injury was accompanied by increased CCL2 expression, suggesting that targeting the CCL2/CCR2 axis could be a new approach for treating pediatric liver cirrhosis." (PMID 39850880, 2024). "Lastly, a prospective clinical study was performed to measure CCL2 and IL13 in human patients with HCC (n = 25) and in patients with cirrhosis of the liver (n = 10)." (PMID 31933479, 2020). "In addition, LSECs induce liver cirrhosis and PHTN by recruiting infiltrated neutrophils in a CXCL1-dependent manner and infiltrated proinflammatory macrophages in a CCL2-dependent manner." (PMID 38713515, 2024).
lymph node metastasis (15 papers, 2016 to 2026). "High levels of Tregs, monocytes, IL10 and chemokines (such as CCL12, CCL2) were also shown to associate with a higher risk of TC lymph node metastases and overall worse prognosis." (PMID 37173925, 2023). "High CCL2 expression correlated strongly with advanced T stage (P = 0.002), clinical stage (P = 0.001), and lymph node metastasis (P = 0.001)." (PMID 42038362, 2026). "CCL2 was reported to promote lymph node metastasis and recurrence in PTC, and IL-10 was related to tumor size and invasion in THCA." (PMID 37798795, 2023). "For example, CCL2/MCP-1 (monocyte chemotactic protein-1) promotes lymph node metastasis in PTC by recruiting TAMs expressing CCR2, and patients with high CCL2 expression are more likely to recurrence." (PMID 35479325, 2022). "CCL2/MCP-1 (monocyte chemotactic protein 1) promotes lymph node metastasis in PTC patients by recruiting TAMs which express CCR2." (PMID 32626535, 2020). "The chemokine CCL2, also known as monocyte chemoattractant protein-1, MCP-1, is released by CAFs, being positively associated with lymph node metastasis." (PMID 33363032, 2020). "For lymph node metastasis, there was no clear association between CCL2, CXCL12 SNPs with lymph node status." (PMID 39703847, 2024). "In addition, preoperative serum CCL2 was significantly correlated with lymph node metastasis." (PMID 33297571, 2020). "CCR2, CCR4, and their respective ligand-mediated pathways, CCR2\CCL2 axis and CCR4\CCL22 axis, are considered to be important mechanisms of lymph node metastasis." (PMID 31672162, 2019). "No evident correlation was found between the expression of CCL2 and the age, gender, and lymph node metastasis of the patients." (PMID 27271610, 2016).
mastitis (15 papers, 2009 to 2025). Inflammation of breast tissue during lactation or postpartum due to an obstructed duct or infection. "CCL2 has previously been implicated in mastitis through several in vitro studies showing that CCL2 can be induced in bovine mammary tissue and epithelial cells by LPS, lipoteichoic acid, or by formalin-killed Staphylococcus aureus." (PMID 29988549, 2018). "The reduced concentrations of the chemotactic protein CCL2 and the humoral response protein LF, are very likely to lead to a reduced lymphocyte chemotaxis towards the bovine mammary gland, leading to greater mastitis susceptibility in cows." (PMID 27310007, 2016). "The proteins crucial for acute mastitis (IL-18, Il-1β, TNFα, CCL2, CCR1) demonstrate low expression." (PMID 34663465, 2021). "In particular, highly virulent mastitis pathogens caused a profound induction of the chemokines CXCL1 and CCL2 as well as the neutrophil growth factor G-CSF." (PMID 29988549, 2018). "Of note, bovine mammary epithelial cells and mammary tissue express CCL2 mRNA in response to LPS stimuli, in agreement with a link between this chemokine and mastitis." (PMID 27713743, 2016). "However, further assessments of CCL2 levels in clinical and subclinical mastitis would be warranted for this purpose." (PMID 29988549, 2018). "Based on these findings, CCL2 may thus be considered as a potential inflammatory biomarker for acute mastitis." (PMID 29988549, 2018). "However, to our knowledge, our study is the first to show that CCL2 is upregulated in vivo during acute mastitis." (PMID 29988549, 2018). "Mastitis induction significantly increased the expression of CCL2 after IMI." (PMID 28740504, 2017). "In this study, we found that SAMC suppressed the secretion of IL-6 as well as Il6, Tnf, Cxcl1, and Ccl2 mRNA levels induced by LPS in HC11 cells, suggesting that SAMC is a key component of AGE that modulates the immune response in an in vivo mastitis model." (PMID 39609525, 2024). "Notably, the study underscores the roles of chemokines CCL8, CCL2, and CXCL10 in immune cell recruitment during mastitis, where their downregulation suggests impaired mammary immune defense that governs Chemokine signalling pathways." (PMID 40196120, 2025).
systemic inflammatory response syndrome (15 papers, 2014 to 2025). SIRS is a serious condition related to systemic inflammation, organ dysfunction, and organ failure. "GA can suppress systemic inflammatory response syndrome (SIRS) associated anti-inflammatory response manifestation via inhibition of CC chemokine ligand 2 (CCL2) production by PMN." (PMID 24963489, 2014). "Another detrimental effect of CCL2 to pathogen defense has been observed in systemic inflammatory response syndrome (SIRS) in mice (modeled via acute pancreatitis)." (PMID 31921102, 2019). "Remarkably, CCL2 and CXCL10, both of which are increased in patients developing a systemic inflammatory response syndrome following SARS-CoV-2 infections, showed a strong hypoxic induction upon subsequent infection with SARS-CoV-2." (PMID 37377965, 2023). "The CD49d+CD11b− N1 neutrophils isolated from SCIDbg mice with mild systemic inflammatory response syndrome (SIRS) secrete the cytokine IL-12 and chemokine CCL3, while CD49d−CD11b+ N2 neutrophils isolated from SCIDbg mice with severe SIRS mainly produce IL-10 and CCL2." (PMID 31727175, 2019).
ulcerative colitis (15 papers, 2009 to 2024). An inflammatory bowel disease involving the mucosal surface of the large intestine and rectum. "Previous data suggest that ulcerative colitis is improved by inhibiting the CCL2/NF-κB/IL-18 pathway, thereby preserving colon function." (PMID 39568749, 2024). "Knockout mice were further used to validate the impact of Ccl2 in ulcerative colitis." (PMID 33540898, 2021). "In contrast, ulcerative colitis presents raised CCL2 levels." (PMID 33540898, 2021). "For instance, the up-regulated expression of chemokines, such as CCL2, CCL3, CCL4, CCL7, CCL8 and CXCL8 has been shown in mucosal biopsies from patients with CD and ulcerative colitis, and this up-regulation correlated with the disease activity." (PMID 19421322, 2009).
Encephalopathy (14 papers, 2016 to 2025). Encephalopathy is a term that means brain disease, damage, or malfunction. "We found that several mediators previously associated with encephalopathy in clinical samples were upregulated in the lung, including CCL2, and IL-6." (PMID 39474424, 2024). "It is also known that patients infected with human orthopneumovirus and presenting neurological symptoms such as encephalitis and encephalopathies, have elevated levels of the proinflammatory cytokines IL-6, IL-8, CCL2, and CCL4 in CSF samples." (PMID 36591299, 2022). "CCL2 blockage considerably reduced the grade of encephalopathy and extended the time to coma, indicating the elevated CCL2 after TAA treatment contributes to the occurrence and development of neurological decline." (PMID 28870240, 2017). "Indeed, elevated levels of IL-6, IL-8 (CXCL8), CCL2, and CCL4 have been reported in cerebrospinal fluid from patients with severe bronchiolitis and hRSV-associated encephalopathy." (PMID 30936869, 2019). "Previous studies have reported that during influenza virus infection there is an increase in the levels of proinflammatory cytokines, such as IL-1β, IL-6, CXCL8, CXCL9, CXCL10, CCL2, and TNF-α, in the CSF of patients who present neurological alterations such as acute encephalitis and encephalopathy." (PMID 36591299, 2022).